INS (insulin)
Diseases named in the same sentence as INS in open-access papers (continued):
Sharing a sentence is not in itself a finding about the gene and the disease.
Obesity (continued). "In Class I obesity cases, the increased insulin level, HOMA index, and sXBP1 levels were consistent with the hypertrophy of adipocytes and their unfavorable metabolic status." (PMID 37219669, 2023). "A meta-analysis involving 379 children (aged 7–19 years) with obesity noted that HIIT significantly impacted the cardiometabolic risk factors, especially HOMA-IR, fasting glucose, and fasting insulin." (PMID 37608837, 2023). "Multivariate linear regression analysis of different types of obesity with insulin secretion and sensitivity." (PMID 36909323, 2023). "The major contributing factors of obesity and T2D/IGT that influence the risk of cancer were increased levels of growth factors such as insulin, IGF-1, steroid and peptide hormones, and inflammatory markers." (PMID 37511200, 2023). "After six months of the western diet, C57BL/6 mice develop obesity, resistance to insulin, and expressed steatohepatitis." (PMID 38434194, 2023). "Individuals with obesity also exhibited elevated levels of leptin, C-reactive protein, insulin, and HOMA-IR index." (PMID 37049393, 2023). "Downregulation of GLUT4 in obesity is an important factor contributing to impaired insulin-stimulated glucose transport in adipocytes." (PMID 36735680, 2023). "The application of propionate to the colon of obese people resulted in a significant reduction in appetite, weight and obesity, as well as improved insulin sensitivity." (PMID 36678236, 2023). "Taken together, our results demonstrate that GCs have an important homeostatic function in regulating insulin sensitivity during obesity which is mediated through the cooperative activation of anti-inflammatory genes by GR and STAT6 in macrophages." (PMID 37080971, 2023). "Vaspin is a novel adipokine derived from visceral adipose tissue identified as a member of the serine protease inhibitor family that exerts insulin-sensitizing effects in obesity." (PMID 36831180, 2023). "Sex-specific models incorporating anthropometric and lipoprotein-related parameters allowed better prediction of ISec and IS in subjects with overweight or obesity than current indices that rely on glucose and insulin alone." (PMID 37047103, 2023). "EGCG improves insulin sensitivity and reduces obesity by epigenetic mechanisms modulating the muscle function." (PMID 37404756, 2023). "Glucose homeostasis, whole-body insulin action, and insulin-mediated glucose uptake into white adipose tissue were improved along with resistance to diet-induced obesity." (PMID 37561580, 2023). "PTP1B inhibitors can serve as insulin mimickers, as well as insulin and leptin sensitizing agents, therefore making them an attractive option to combat T2D and obesity simultaneously, which represents an advantage over existing therapies to date." (PMID 37628991, 2023). "Upregulation of these inflammatory mediators in obesity can impair insulin action and glucose uptake in peripheral tissues." (PMID 38037591, 2023). "These phytonutrients showed potential anti-obesity and anti-diabetes effects by altering the following physiological pathways such as controlling hunger, metabolism, and insulin sensitivity." (PMID 37835263, 2023). "Common conditions as obesity and old age modify glucose tolerance and insulin sensitivity of animals." (PMID 36830532, 2023). "Again, the effects of obesity paralleled those observed on the insulin responses to the glucose and protein challenges, possibly reflecting resistance to postprandial insulin effects in obese individuals." (PMID 37736753, 2023). "Most clinical and biochemical variables were affected by obesity, whereas hyperandrogenemia affected only blood pressure and insulin concentration." (PMID 37763087, 2023). "A recent cohort study found a negative association between hypomethylation of the LEP gene promoter, obesity, lipid profile modification, and low insulin sensitivity." (PMID 37375898, 2023).
Obesity (continued). "Many studies highlight the impact that the ketogenic diet has on restoring insulin sensitivity in people with T2D and obesity." (PMID 38068805, 2023). "The basic mechanism for obesity is excess glucose and insulin; glucose stimulates insulin release allowing its utilization by the muscles and storage of the excess as fat." (PMID 36984824, 2023). "We found that caffeine has favorable effects on the metabolic syndrome in the rat model, chiefly on the insulin resistance and obesity components." (PMID 36740696, 2023). "Based on the translational results of insulin hypersecretion, we proposed that beta-cell overstimulation contributes to hyperinsulinemia in young children with obesity and high palmitate concentrations." (PMID 37623862, 2023). "Decreased insulin sensitivity correlates with immune modifications during pregnancy, such as increased circulating TNF-alpha and IL-6, which are believed to trigger obesity-associated metabolic inflammation." (PMID 37515062, 2023). "Such milk protein, when orally administered, can pass unchanged through the stomach, exerting a protective effect against inflammation and insulin resistance, which are typical features of obesity." (PMID 37513560, 2023). "In the liver, there is an accumulation of fats that precedes T2D and is related to obesity; namely, the reduction in hepatic insulin sensitivity leads to hyperglycemia." (PMID 38137918, 2023). "Oral transplantation of fecal microbiota in combination with supplementation with low-fermentable fiber improved insulin sensitivity in patients with severe obesity and metabolic syndrome." (PMID 38068759, 2023). "In this study, we measured BCKAs, glutamate/glutamine and uric acid and explored their relationships individually with changes in weight and insulin sensitivity before and after a lifestyle intervention in adolescents with obesity." (PMID 36415168, 2023). "OGTT ClI was lower in youths with obesity at puberty along with insulin sensitivity and greater secretion." (PMID 37834412, 2023). "Nuclear genes, including calpain 10 (CAPN10), cytochrome family P450, insulin (INS) gene, androgen receptor (AR), fat mass obesity (FTO) gene, and follicle-stimulating hormone receptor (FSHR) gene, have been shown to be associated with PCOS." (PMID 37674615, 2023). "Consistent with the observed increase in obesity, insulin levels in LEPTIN−/− pigs were significantly increased at 12- and 18-months of age." (PMID 37705071, 2023). "Running on a treadmill at 65% of VO2max 3 times/week for 4 weeks under moderate hypoxia (~ 2740 m) improved fasting insulin levels compared with baseline in overweight individuals and individuals with obesity." (PMID 36441492, 2023). "Body weights, calorie intake, and other critical parameters related to obesity and insulin resistance were measured during the 16-week feeding period." (PMID 37732123, 2023). "According to the 2012 OSCA recommendations (Obesity Services for Children), fasting insulin levels should be interpreted based on the degree of sexual maturation." (PMID 37892696, 2023). "Univariable linear regression analysis of the whole study population showed that obesity; the presence of HT, coronary artery disease and T2DM; insulin use; NT-proBNP; eGFR and indexed LVM were associated with impaired longitudinal PS (all P < 0.05)." (PMID 37542280, 2023). "Following FMT, two research studies (involving 91 patients) examined how fasting insulin affected obesity and other metabolic illnesses." (PMID 37511862, 2023). "The patho-physiology creates one vicious cycle leading to another, with obesity leading to chronic low-grade inflammation, enhancing gutmicrobiota dysbiosis, insulin and leptin resistance." (PMID 37795371, 2023). "Nevertheless, exercise-induced decreases in insulin secretion during concomitant increases in insulin sensitivity are consistently found in individuals with prediabetes and/or obesity, as well as in healthy people." (PMID 37127822, 2023).
Obesity (continued). "Adiponectin, typically decreased in obesity, plays a role in insulin sensitization and has anti-inflammatory properties." (PMID 38264286, 2023). "Deterioration of brain functionality through obesity has also been suggested to be due to another low-grade systemic inflammation mechanism, namely insulin resistance." (PMID 36767806, 2023). "Obesity is characterized by the abnormal deposition of fat in the body, leading to metabolic abnormalities, including fatty liver, elevated plasma insulin/leptin levels, and dyslipidemia." (PMID 36902181, 2023). "As previously reported, diabetic mice in the present study exhibited a phenotype of obesity, elevated plasma glucose, a modest increase in plasma triglycerides, and decreased insulin sensitivity." (PMID 37850093, 2023). "The role of SCFAs in preventing obesity was demonstrated several years ago by in vivo studies which emphasized the role of FFAR2 in suppressing insulin signalling in adipocytes, thus halting the accumulation of lipids in AT." (PMID 37049562, 2023). "In the presented study, using the AUCROC analysis for obesity, we showed an insulin cut-off of 9.5 μIU/mL, a C-peptide cut-off of 2.3 ng/mL and a HOMA-IR cut-off of 1.8." (PMID 37373485, 2023). "Recently, we addressed that F4MKO mice are obesity-resistant and exhibit enhanced energy expenditure, insulin sensitivity, and exercise capacity." (PMID 37770480, 2023). "A defective SCD1 gene leads to resistance to diet-induced obesity, increased insulin sensitivity, and increased metabolic rate." (PMID 37049884, 2023). "Ethanolic extract of Cosmos caudatus kunth leaf decreased weight growth and enhanced levels of obesity indicators such as lipid profile, insulin, ghrelin, and adiponectin in rats fed a high‐fat diet, while also improving fecal fat excretion." (PMID 38455221, 2023). "The same mixed results for glycemia can be seen in healthy volunteers with overweight/obesity, while resistant starch seems to improve postprandial insulin responses." (PMID 37242267, 2023). "Obesity is a major element in the development of resistance to insulin, which has been connected to anovulation, an etiological factor of the stated syndrome." (PMID 37854752, 2023). "It was also able to reverse β‐cell dysfunction promoted by incubation with the serum or plasma from obese subjects, indicating a therapeutic potential for this pathway in the prevention of insulin secretion failure in obesity." (PMID 37060190, 2023). "As a metabolic abnormality, obesity leads to a series of changes in insulin, IGF-1, sex hormones, IGFBPs, and adipokines." (PMID 36755926, 2023). "The study also demonstrated that insulin-dependent factors were decreased in obesity as a result of exercise." (PMID 38136166, 2023). "In conclusion, in individuals with obesity, T2D emerges with reduced insulin sensitivity followed by impaired β-cell function and reduced β-cell mass." (PMID 38026205, 2023). "In mice, genetic lowering of the number of insulin genes expressed and of circulating insulin levels prevented or partially reversed diet-induced obesity." (PMID 36904300, 2023). "Individuals with obesity experience a reduction in adiponectin, allowing for a more proinflammatory and insulin-resistant environment." (PMID 36766750, 2023). "Obesity-resistant rats displayed insulin-dependent changes in odor-sniffing activity; however, intraperitoneal insulin injections (mimicking a meal-induced insulin surge) in obese rats did not alter odor sniffing activity of high-fat diet." (PMID 36409650, 2023). "In a mice model of obesity and diabetes, treatment with another PPARγ agonist, rosiglitazone, improved insulin sensitivity, increased serum adiponectin levels, and reduced inflammation in adipose tissues." (PMID 37627590, 2023). "These experiments suggest that Sxc modestly increases insulin secretion and enhances glucose disposal in mice on a chow diet initially, while these effects disappear during obesity." (PMID 37650924, 2023).
Obesity (continued). "Several common abnormalities in the microenvironment of obesity impairing insulin sensitivity, such as lipid accumulation, oxidative stress, inflammation, ER stress, and mitochondrial dysfunction, induce a negative impact on autophagy as well." (PMID 37152942, 2023). "Loss of SEL1L in myocytes leads to reprogramming of systemic metabolism, including enhanced adipocyte beigeing, increased insulin sensitivity, and resistance to diet-induced obesity, partly through the action of myocyte-derived FGF21." (PMID 37535424, 2023). "The release of incretins augments insulin secretion in healthy individuals; however, this action diminishes in cases of obesity and T2DM." (PMID 37298274, 2023). "MAPKs cause phosphorylation of nuclear and cytoplasmic substrates, leading to adaptation to the new diet by regulating insulin signaling, blood glucose concentration, and obesity." (PMID 36984693, 2023). "SIRT6 plays an important role in glucose homeostasis by increasing insulin secretion parallel with inhibition of gluconeogenesis and lipogenesis and suppression of obesity-induced inflammation and insulin resistance." (PMID 37047134, 2023). "In obesity, the suppression of insulin signal and inflammation in WAT enhance the chronic release of FFAs and other pro-inflammatory mediators." (PMID 36829858, 2023). "An increase in body weight, blood glucose, and insulin levels are the hallmarks of obesity progression." (PMID 37334370, 2023). "Hyperinsulinemia, also known as dysregulated insulin production and/or clearance, is a prevalent feature of obesity and metabolic diseases that results in persistently increased insulin levels without hypoglycemia." (PMID 38068822, 2023). "Although protein metabolism at the whole-body level is less sensitive to insulin action, the obesity-related effect related to insulin resistance and its impact on the locomotor, weight-bearing, and skeletal muscle protein cannot be ignored." (PMID 37252233, 2023). "The obesity, fat accumulation, and insulin insensitivity in LepR-Cre Slc7a5fl/fl mice were ameliorated in LepR-Cre Slc7a5fl/fl Tsc1fl/+ mice." (PMID 36862514, 2023). "Fascinatingly, these mice were also secluded from obesity-induced inflammation and insulin confrontation." (PMID 36831151, 2023). "Phosphate, from a diabetes and obesity perspective, is especially interesting, as numerous reports link phosphate to insulin action." (PMID 36984860, 2023). "High fat and glucose levels can trigger the secretion of insulin from pancreatic β cells and PTMs of a series of kinases, generate fatty acids that are taken up by adipose tissue and induce obesity." (PMID 37244925, 2023). "Regarding the metabolic biochemical and clinical parameters, we observed that the individuals with class 3 obesity had higher mean HbA1c, insulin, and DBP, and lower mean HDL-c." (PMID 37334132, 2023). "Individuals with obesity (BMI >30 kg/m2 and FG <7 mmol/l) exhibited a wide range of insulin sensitivities (GIR 0.8–11.1 mg kg–1 min–1)." (PMID 36790478, 2023). "The GLP-1 receptor agonists (GLP-1RA) have emerged as the second-generation anti-obesity medications due to their metabolically beneficial effects to stimulate insulin secretion while suppressing food intake." (PMID 37511253, 2023). "Exosomes released from obesity adipose tissue containing less miR-141-3p inhibit the insulin sensitivity and glucose uptake." (PMID 37534206, 2023). "A study in male Wistar rats also indicated that the consumption of omega-3 fatty acids in high-fructose diet-induced obesity rats showed improved insulin sensitivity." (PMID 37764688, 2023). "Obesity provokes a state of chronic low-grade inflammation, leading to the disruption of insulin signaling pathways and further compromising insulin sensitivity." (PMID 37621846, 2023). "Various studies performed using the mouse model explained the mechanism of propionic acid in preventing obesity by inhibiting food intake, increasing insulin sensitivity, and energy expenditure." (PMID 37861729, 2023).
Obesity (continued). "Another study found that liraglutide and semaglutide improved glucose tolerance and insulin sensitivity, reduced body weight gain and excessive lipid accumulation, and enhanced muscle atrophy in a high-fat diet model of obesity by activating the SIRT1 pathway." (PMID 38201893, 2023). "On the other hand, adiponectin is a plasma protein that decreases when obesity occurs and correlates with insulin sensitivity." (PMID 37513964, 2023). "Cluster 4 comprised 22 items, that represented dysfunction and disorders of the host’s internal environment, such as “dysbiosis”, “obesity”, “blood-pressure”, “insulin sensitivity”, “hypertension”, and “dysfunction” (shown in yellow)." (PMID 37110325, 2023). "These mice are characterized by high energy input and low energy output, which triggers early-onset obesity, insulin resistance, lower-than-normal insulin levels, and hypothermia." (PMID 37374323, 2023). "Mice with adipocyte-specific inhibition of autophagy are resistant to diet-induced obesity and show improved insulin sensitivity." (PMID 37876013, 2023). "Absence of Slc6a2 receptor helps to maintain the abundance of norepinephrine, thus promoting heat generation and reversal of obesity along with improving insulin sensitivity." (PMID 36718668, 2023). "It will be interesting to determine if restoring insulin sensitivity inside IR immune cells during obesity is another mechanism of action by which metformin can boost immune cell clearance of SARS-CoV-2." (PMID 36992811, 2023). "The latest research demonstrated that hepatocyte-derived MANF plays a crucial role in increasing insulin sensitivity and that the systemic injection of MANF protein greatly enhanced insulin sensitivity in mice exhibiting obesity." (PMID 36936164, 2023). "On an HFD, global Mogat1 deletion contributed to obesity, insulin sensitivity, and glucose intolerance." (PMID 37238090, 2023). "In the present study, we evaluated the metabolic beneficial effects and anti-diabetic properties by using the animal model with obesity and impaired insulin sensitivity." (PMID 37426418, 2023). "This subgroup resembled the obesity-related subgroup identified in the first approach, particularly mean BMI and mean HbA1c were high, while insulin resistance was moderate." (PMID 37402743, 2023). "To evaluate the role of the glucose–insulin axis in driving obesity, we administered glucose to KHK-KO mice or control mice." (PMID 37482773, 2023). "This suggests that macrophage ER is important for suppressing inflammation and maintaining insulin sensitivity, making it a potential therapeutic target to combat obesity and IR." (PMID 37153549, 2023). "Among the adipokines, adiponectin and particularly its HMW oligomers have beneficial properties such as anti-inflammatory, antioxidative, and insulin-sensitizing effects and are reduced in obesity." (PMID 36674646, 2023). "The most-cited topics have mainly focused on insulin sensitivity, DNA methylation, nutritional epigenomics, obesity, human pancreatic islets, and early life." (PMID 37201099, 2023). "The observed relationships between HDL cholesterol, triglycerides, and insulin levels within the group of children with obesity were evident only during the first visits." (PMID 37892696, 2023). "For example, previous studies employing animal models showed that modulating GM had salutary effects on obesity, insulin sensitivity, and type 2 diabetes (T2D)." (PMID 36900540, 2023). "Along this line, the significance of tissue-specific GR signaling in obesity has been reported; for example, liver GR signaling accelerates fat accumulation in adipose tissue and worsens systemic insulin sensitivity in a 2-week DEX treatment model." (PMID 36917179, 2023). "Obesity-induced hepatic Th17 cells and IL-17A signaling have consistently been reported to impair insulin sensitivity and promote hepatic steatosis and fibrosis in both HFD-fed mice and patients with NAFLD/NASH." (PMID 37140993, 2023).